GABPB1-IT1 (GABPB1 intronic transcript)
Synonyms: FLJ10038
Gene: Long non-coding RNA gene on chromosome 15 (50,348,936 to 50,354,861, reverse strand). Ensembl gene ENSG00000285410.
Diseases named in the same sentence as GABPB1-IT1 in open-access papers:
GABPB1-IT1 is named in the same sentence as 2 diseases in open-access papers, as found by Europe PMC text mining. Sharing a sentence is not in itself a finding about the gene and the disease.
GABPB1-IT1 shares sentences with these, for which no sentence is quoted: breast carcinoma (1 paper); breast tumor (1).